PGR (progesterone receptor)
Diseases named in the same sentence as PGR in open-access papers (continued):
Sharing a sentence is not in itself a finding about the gene and the disease.
amenorrhea (5 papers, 2002 to 2021). The absence of menses in a woman who has achieved reproductive age. "DFS differences between amenorrhea categories were larger for patients with ER/PgR positive tumours." (PMID 12087454, 2002). "We previously published data from IBCSG Trial VI according to amenorrhea suggesting that the endocrine effects of chemotherapy alone are insufficient for the younger age group with ER/PgR positive tumours." (PMID 12087454, 2002). "Ulipristal is a selective progesterone receptor modulator (SPRM) have been successful to reach amenorrhea in 70-80% of women, with a faster median onset of 4 days to reach it and less adverse effects when compared to GnRH analogues; however, this drug was not tested in women under 18 years." (PMID 25609056, 2015). "It is presumedthat upregulation of endometrial progesteronereceptors by estrogen in oral contraceptives accountfor this finding.A previous study found that endometrialglandular progesterone receptor immunoreactivity wassimilar in patients experiencing bleeding or amenorrhea onDMPA." (PMID 17093355, 2006). "Ulipristal acetate (UPA) a selective progesterone receptor (PR) modulator (SPRM) reduce the size of UFs, inhibit ovulation and lead to amenorrhea." (PMID 31754172, 2019). "Cases were not reported with amenorrhea by this study where most of the medical managements, UPA, GnRH, agonist selective progesterone receptor modulators (SPRMs) of the disease were faced." (PMID 34257678, 2021).
astrocytoma (5 papers, 2013 to 2023). "Although LPAR1 mRNA expression was associated with poor prognosis only in grade III astrocytomas, we were interested in evaluating whether there was a correlation between PGR and LPAR1 expression." (PMID 33916643, 2021). "It was reported that progesterone-receptor isoforms are expressed in two cell lines (U373 and D54) derived from high-grade human astrocytoma." (PMID 23530939, 2013). "Patients with astrocytoma grades III and IV with low expression of PGR and PRKCA mRNA showed higher survival than those with high expression." (PMID 36358843, 2022).
clear cell carcinoma (5 papers, 2013 to 2024). "OC subtypes display different steroid hormone receptor profiles; for example, the endometrioid subtype is more likely to exhibit estrogen receptor (ER) and/or progesterone receptor (PR) positivity, whereas the clear cell carcinoma subtype mainly expresses estrogen receptor beta (Erβ)." (PMID 37754524, 2023). "The absence of both WT1 and PgR positivity suggests mucinous or clear cell carcinoma." (PMID 38573494, 2024).
female reproductive cancers (5 papers, 2013 to 2024). "To clarify the role of +331G/A PgR polymorphism in female reproductive cancers, we performed a meta-analysis of all of the eligible case-control studies to derive overall cancer risk associated this polymorphism." (PMID 23349706, 2013). "Therefore, to clarify the role of the PRPGINS PgR polymorphism in female reproductive cancers, we performed a meta-analysis of all eligible case–control studies to derive the overall cancer risk associated with this polymorphism." (PMID 35839271, 2022). "Progesterone receptor alienation leads to increased susceptibility to female reproductive cancer." (PMID 35839271, 2022). "The present study performed a meta-analysis to examine whether the progesterone receptor gene PROGINS polymorphism was a susceptibility factor for female reproductive cancer." (PMID 35839271, 2022). "The association between PgR mutations and female reproductive cancer varies between races." (PMID 35839271, 2022). "Functional analysis substantiated that 39 of these genes played key roles in tumor initiation and cancer progression, with 2 specific genes (ESR1 and PGR) being shared across the gynecologic cancers." (PMID 38248117, 2024). "The progesterone receptor is known as a positive marker for overall survival of different gynecologic cancer types." (PMID 36769131, 2023). "Our meta-analysis showed that the progesterone receptor gene Alu insertion and the V660L polymorphism contained in the PROGINS polymorphism were susceptibility factors for female reproductive cancer." (PMID 35839271, 2022).
leiomyosarcoma (5 papers, 2012 to 2023). An uncommon, aggressive malignant smooth muscle neoplasm, usually occurring in post-menopausal women. "Both PGR and ER have also been reported as positive prognostic markers for uterine leiomyosarcoma." (PMID 38066476, 2023). "ER and PGR are also reported to be positive prognosticators of uterine leiomyosarcomas." (PMID 23497154, 2013). "The original tumor was a high-grade leiomyosarcoma with large low-grade and leiomyoma-like areas and whose constituent cells displayed intense nuclear immunoreactivity for both estrogen receptor (ER) and progesterone receptor (PR) in approximately 30% of cells." (PMID 23119198, 2012). "Specifically, genes such as PGR, TRIM22, BOK, NAALADL1, AFAP1L2, and ESR1 showed MSS values greater than 5 in uterine leiomyosarcoma samples." (PMID 38066476, 2023).
serous ovarian cancer (5 papers, 2014 to 2023). "The expression level of the progesterone receptor (PGR) plays a crucial role in determining the biological characteristics of serous ovarian carcinoma." (PMID 37569592, 2023). "Low-grade serous ovarian cancer seems to be mediated through activation of the MAPK pathway via RAS/RAF and is associated with high levels of estrogen receptor and progesterone receptor expression." (PMID 35873467, 2022). "A recent study by the Ovarian Tumor Tissue Analysis consortium (OTTA) focused on expression of ERα and the progesterone receptor (PR), and in a large series only strong expression of PR, but not ERα, was correlated to increased survival in high-grade serous ovarian cancer." (PMID 25226589, 2014). "Therefore, we suggest that the expression of progesterone receptor may be a prognostic biomarker in non-serous ovarian cancer rather than serous ovarian cancer." (PMID 28415663, 2017).
Anxiety (4 papers, 2007 to 2022). Intense feelings of nervousness, tension, or panic often arise in response to interpersonal stresses. "Mifepristone is known to be a competitive progesterone receptor antagonist, and progesterone may also serve to modulate anxiety-like behavior." (PMID 33803557, 2021). "While RU486 has a potential to inhibit progesterone receptor, these results suggest that elevated HPA activity immediately after weaning heightens anxiety-related behaviors by acting on the PFC." (PMID 30850750, 2019).
cyst (4 papers, 2007 to 2024). A sac-like closed membranous structure that may be empty or contain fluid or amorphous material. "By immunohistochemistry, estrogen receptor (ER), progesterone receptor (PR), PAX-8, and WT1 were positive in the epithelial lining of the cyst, lending support to a possible Müllerian origin." (PMID 28070193, 2016). "However the cyst epithelium appears to be capable of responding to progesterone stimulation, since we (O. L. Tan and J. S Fleming, unpublished observations) and others have shown strong expression of progesterone receptor protein in the nuclei of benign cystadenomas in both mouse and human." (PMID 17425809, 2007). "Immunohistochemical staining: The epithelium lining the cyst wall diffusely and strongly expressed SAM, progesterone receptor (PR), ER, WT1 and PAX8, was negative for calretinin, and had low proliferation of ki-67." (PMID 39605896, 2024).
endometrial polyp (4 papers, 2013 to 2019). A benign nodular lesion protruding above the surface of the endometrium. "In the glandular epithelium of endometrial polyps, the immunohistochemical expression of the estrogen receptor (ER) and progesterone receptor (PR) is higher than that in the adjacent endometrium." (PMID 24932265, 2014).
endometrioid tumor (4 papers, 2014 to 2025). A benign, borderline, or malignant epithelial tumor of the female reproductive system characterized by the presence of glands and/or cysts lined by neoplastic cells that resemble endometrial cells. "We found that MSI tumors were more likely to present lower ER levels and a trend towards lower PgR, which contrast with the fact that endometrioid tumors are prototypically associated with estrogen stimulation and generally express both receptors." (PMID 25026289, 2014). "Its efficacy has primarily been observed in low-grade endometrioid tumors and is dependent on the status of estrogen receptor (ER) and progesterone receptor (PgR)." (PMID 41552063, 2025). "Among cases in the endometrioid tumor group, PGR expression was also found to be downregulated in grade 3 vs. grade 1 tumors (P<0.05 by one-way ANOVA followed by the Holm-Sidak method for pairwise comparisons)." (PMID 25229191, 2014).
leukemia (4 papers, 2011 to 2022). A malignant (clonal) hematologic disorder, involving hematopoietic stem cells and characterized by the presence of primitive or atypical myeloid or lymphoid cells in the bone marrow and the blood. "Progesterone receptor methylation has been reported in leukemia and solid cancers." (PMID 21760961, 2011).
neurofibroma (4 papers, 2011 to 2019). An intraneural or extraneural neoplasm arising from nerve tissues and neural sheaths. "The functions of oestrogen receptor and progesterone receptor have been reported; however, the contribution of AR in neurofibroma progression needs further clarification." (PMID 31852972, 2019). "Progesterone receptor expression in neurofibromas has been reported." (PMID 26545719, 2015). "Immunostaining studies have provided support for this hypothesis by identifying the progesterone receptor in neurofibromas." (PMID 22943186, 2012). "Immunostaining studies identified the progesterone receptor in neurofibromas." (PMID 21542925, 2011).
pancreatic cancer (4 papers, 2016 to 2025). "Our results provide the initial evidence for the participation of PGR in this process, highlighting its potential as a therapeutic target for energy metabolism in pancreatic cancer." (PMID 38424455, 2024). "Interestingly, both PGR expression and PGR activation could influence macropinocytosis levels and PDAC growth in our observations, indicating that the mechanism of PGR functions in pancreatic cancer cells might be greater complex than previously recognized." (PMID 38424455, 2024).
uterine cancer (4 papers, 2009 to 2025). Primary or metastatic malignant neoplasm involving the uterine corpus and/or the cervix. "For instance, the endometrioid subtype, which accounts for approximately 80% of uterine cancers, retains estrogen receptor and progesterone receptor status and is responsive towards progestin therapy." (PMID 33926541, 2021). "For instance, the influence of GLP1R expression on estrogen or progesterone receptor-positive tumors might explain differential survival outcomes in cancers like breast and uterine carcinomas." (PMID 39777709, 2025). "Interestingly, uterine expression of HOPX in the progesterone receptor knockout (PRKO) mouse has been found to be increased by injection of progesterone; a steroid hormone known to decrease the risk of developing uterine cancer." (PMID 19200380, 2009).
uterine sarcoma (4 papers, 2011 to 2024). "The immunophenotype is similar to that of an undifferentiated uterine sarcoma with usually loss of expression of the cell differentiation markers estrogen receptor, progesterone receptor and CD10." (PMID 21663687, 2011). "Hormonal therapy in uterine sarcoma with estrogen receptor (ER) and progesterone receptor (PR) expression is another targeted treatment option." (PMID 39796641, 2024). "Despite emerging reports about the potential benefit of hormonal therapy, selective estrogen and progesterone receptor modulators and aromatase inhibitors, for uterine sarcoma, there is a paucity of information regarding the application of these therapies to sarcomas arising at other sites." (PMID 24255838, 2013).
uterine tumors (4 papers, 2017 to 2023). "As a tumour of the uterus, hormone receptor expression is often recorded at diagnosis, with both oestrogen receptor (ER) and progesterone receptor (PR) levels expressed at similar rates (35−87% and 17−80%, respectively)." (PMID 35326717, 2022).
abortion (3 papers, 2010 to 2022). the ending of pregnancy by removing a fetus or embryo before it can survive outside the uterus. "That is why we have included common PGR polymorphism in our study of the risk of spontaneous abortion." (PMID 30116270, 2018). "Next factors that can also be considered when predicting the risk of spontaneous abortion are SNPs in TLR2, TLR4, IL-6, IL-8, and PGR genes." (PMID 30116270, 2018). "In our previous study using human endometrial samples from different patients with recurrent spontaneous abortion cohort, we also observed progesterone resistance as revealed by defective PGR signaling, with normal PGR protein level but diminished transcriptional PGR activity." (PMID 35244538, 2022).
angiomyxoma (3 papers, 2008 to 2025). A benign soft tissue neoplasm characterized by the presence of neoplastic spindle and stellate cells, and vascular proliferation in a myxoid stroma. "A case of aggressive angiomyxoma of the vulva growing during pregnancy and strong progesterone receptor positivity has been reported." (PMID 40428263, 2025). "The estrogen and progesterone receptor positivity suggests that aggressive angiomyxoma might be hormone dependent as rapid growth has been observed during pregnancy." (PMID 18755035, 2008). "Male angiomyxoma may be positive for estrogen and progesterone receptor." (PMID 21143833, 2010).
bladder cancer (3 papers, 2017 to 2023). "Similarly, the progesterone receptor (PGR), another hormone-related target, was not considered for further validation due to the minimal expression of this protein in bladder cancer." (PMID 37608369, 2023).
COVID-19 (3 papers, 2021 to 2022). A disease caused by infection with severe acute respiratory syndrome coronavirus 2. "We reviewed studies surrounding polymorphic Alu retrotransposons in ACE, PGR, PLAT, and F13B that have been either mechanistically linked to and/or associated with clinical conditions relevant to COVID-19." (PMID 33390179, 2021). "Here, we briefly summarize and examine known Alu polymorphisms in ACE, PGR, PLAT, F13B regarding their biological functions, roles in disease, and implications for COVID-19." (PMID 33390179, 2021). "Regarding critical pathways related to SARS-CoV-2 infection, progesterone signaling can upregulate ACE2 in endothelial cells, thus implicating the differential response to progesterone via PGR Alu I/D in the clinical outcome of COVID-19 as it shares an intricate connection to the RAAS system." (PMID 33390179, 2021). "Using network pharmacology, we identified 7 core targets of curcumol against COVID-19 and COAD, including GABRD, GABRP, BCHE, CYP3A4, PGR, HSD17B2, and SLC6A3." (PMID 35967794, 2022).
esophageal cancer (3 papers, 2012 to 2020). A primary or metastatic malignant neoplasm involving the esophagus. "Esophageal cancer cells also express other sex hormone receptors, such as androgen receptor, progesterone receptor, and so on." (PMID 32793111, 2020).
female infertility (3 papers, 2018 to 2025). Diminished or absent ability of a female to achieve conception. "Our earlier studies have reported that overactivation of TGFB receptor 1 (TGFBR1) in the mouse uterus using progesterone receptor (Pgr)-Cre recombinase causes female infertility, defective decidualization, and reduced uterine gland formation, a developmental milestone of postnatal uterus." (PMID 30550590, 2018). "Disruption of PGR in zebrafish has been shown to result in female infertility due to unsuccessful ovulation, raising intriguing questions about whether the absence of PGR might also affect early follicle growth." (PMID 40281968, 2025).
gastrointestinal stromal tumor (3 papers, 2011 to 2025). "The purpose of this study is to clarify the prognostic significance of expression of Skp2 related to age, gender and female steroid hormone receptors (ER and PGR) in non-gastrointestinal stromal tumor (non-GIST) STS." (PMID 23497154, 2013). "Immunohistochemical analysis showed that the tumors were positive for vimentin, WT1, progesterone receptor (PR), and variably for estrogen receptor (ER), CD56, inhibin, and calretinin, while being negative for markers of epithelial, melanocytic, and gastrointestinal stromal tumors." (PMID 40828576, 2025).
Gynecomastia (3 papers, 2021 to 2024). Abnormal development of large mammary glands in males resulting in breast enlargement. "Side effects come along with its affinity to androgen receptor leading to gynecomastia and erectile dysfunction in male and to progesterone receptor leading to menstrual irregularity in female." (PMID 33995277, 2021). "Furthermore, spironolactone exhibits anti-androgenic effects due to its activity as a progesterone receptor agonist and androgen receptor antagonist, which can result in gynecomastia, breast tenderness, menstrual irregularities, impotence, and decreased libido, especially at higher doses." (PMID 39518537, 2024). "In addition, spironolactone has a similar structure to progesterone and acts as a progesterone receptor (PR) agonist and androgen receptor (AR) antagonist, therefore promoting sexual side effects including gynecomastia and impotence in men and disruption of the menstrual cycle in women." (PMID 36768761, 2023).
hepatocellular carcinoma (3 papers, 2014 to 2022). A malignant tumor that arises from hepatocytes. "Increased expression of PRMT1 has been implicated in the tumorigenesis of multiple cancers including progesterone receptor positive breast cancer, hepatocellular carcinoma (HCC), neuroblastoma, and pancreatic cancer." (PMID 33440687, 2021).
metabolic syndrome (3 papers, 2011 to 2025). A cluster of metabolic risk factors for CARDIOVASCULAR DISEASES and TYPE 2 DIABETES MELLITUS. "In those studies, ERα gene silencing of more than 80% in the VMN abolished female sexual proceptivity and receptivity, attenuated progesterone receptor expression, and induced metabolic syndrome." (PMID 39911518, 2025).
metaplastic breast carcinoma (3 papers, 2013 to 2025). A group of invasive breast carcinomas characterized by the presence of an adenocarcinomatous component which is admixed with a dominant component that is composed of squamous cells, spindle cells, or mesenchymal cells. "Metaplastic breast carcinoma most commonly exhibits triple-negative receptors via the absence of estrogen receptor (ER), progesterone receptor (PR), and human epidermal growth factor receptor 2 (HER2)." (PMID 38957239, 2024).